ITGB4 (integrin subunit beta 4)
Diseases named in the same sentence as ITGB4 in open-access papers (continued):
Sharing a sentence is not in itself a finding about the gene and the disease.
pancreatic cancer (continued). "In particular p-ITGB4, a member of the integrin family, was increased at least 2-fold in high-invasive vs. weak-invasive pancreatic cancer cells." (PMID 31242404, 2020). "The present study revealed that ITGB4 plays a crucial role in the tumorigenesis of pancreatic cancer." (PMID 31242404, 2020). "The significantly higher expression of ITGB4 in pancreatic cancer vs. normal tissues was further confirmed by semi-quantitative RT-PCR (p < 0.05)." (PMID 31242404, 2020). "The IHC analysis showed that the expression of ITGB4 was highly increased in pancreatic cancer tissues." (PMID 31242404, 2020). "siRNA silencing of ITGB4 expression inhibited the migration and invasion abilities of pancreatic cancer cells." (PMID 31242404, 2020). "Next, the transwell assay was conducted to analyze the effect of ITGB4 on the invasion ability of pancreatic cancer cells." (PMID 31242404, 2020). "In the current study, we further investigated the role of ITGB4 and its phosphorylation at Y1510 in the tumorigenesis of pancreatic cancer." (PMID 31242404, 2020). "Therefore, modulation of ITGB4 expression or its phosphorylation at Y1510 represents a potential novel therapeutic approach for pancreatic cancer." (PMID 39169946, 2024). "Notably, ITGB4 exhibits high expression levels in oral squamous cell carcinoma, gliomas, and pancreatic cancer." (PMID 39169946, 2024). "ITGB4 promotes cell migration and invasion in pancreatic cancer; however, its exact role in these processes remains unclear." (PMID 37686626, 2023). "This suggests that ITGB4 may interact with integrin α6 or function independently to trigger downstream signaling cascades involved in pancreatic cancer development, invasion, and metastasis." (PMID 31242404, 2020). "Overall, our study not only revealed the pivotal role of ITGB4 and its Y1510 phosphorylation in the tumorigenesis of pancreatic cancer but it also provided a rationale for targeting ITGB4 or its Y1510 phosphorylation, as a novel therapeutic option for pancreatic cancer." (PMID 31242404, 2020). "In the current study, we aimed to determine whether ITGB4 is involved in pancreatic tumorigenesis and invasion/migration of pancreatic cancer cells as well as to elucidate the molecular mechanism of p-ITGB4-Y1510 in pancreatic cancer." (PMID 31242404, 2020). "In our previous study, we found that ITGB4 was highly expressed in high-invasive metastatic pancreatic cancer cell line PC-1.0 compared to low-invasive cell line PC-1, implying that ITGB4 may be functionally involved in the tumorigenicity of pancreatic cancer." (PMID 31242404, 2020). "We then estimated the prognostic value of ITGB4 in patients with pancreatic cancer." (PMID 31242404, 2020). "Targeting ITGB4 or its phosphorylation at Y1510 may be a novel therapeutic option for pancreatic cancer." (PMID 31242404, 2020). "Since the phosphorylation of integrin is important for its activity, we analyzed whether the phosphorylation of ITGB4 at Y1510 was increased in pancreatic cancer tissues." (PMID 31242404, 2020). "Thus, in this study, we first examined whether ITGB4 was highly expressed in 176 specimens of pancreatic cancer tissues compared with 171 specimens of normal pancreatic tissues." (PMID 31242404, 2020). "However, it remains unclear whether the phosphorylation of ITGB4 at Y1510 is involved in the tumorigenicity of pancreatic cancer." (PMID 31242404, 2020). "However, the exact role of ITGB4 in pancreatic tumorigenesis and pancreatic cancer invasion and metastasis remains unclear." (PMID 31242404, 2020). "During cellular adhesion, the interaction between ITGB4 and the ECM activates the MAPK signal transduction pathway, playing an important role in the progression of pancreatic cancer." (PMID 31242404, 2020). "Finally, the TCGA and GTEx databases were used to verify a weak, but significant inverse correlation of CD45 (PTPRC gene), CCR5 and CCR1 with ITGB4 in human pancreatic cancer, but not normal pancreas." (PMID 36932441, 2023).
pancreatic cancer (continued). "The results of our study showed that after the inhibition of ITGB4 phosphorylation at Y1510 the level of p-ERK1/2 was significantly decreased, implying that ERK1/2 promotes the invasion and metastasis of pancreatic cancer cells via the MAPK/MEK/ERK signaling pathway." (PMID 31242404, 2020). "Database analyses also revealed a significant negative correlation between ITGB4 and PTPRC (CD45 gene), CCR5 as well as CCR1 in pancreatic cancer, but not normal pancreas tissue." (PMID 36932441, 2023).
glioma (14 papers, 2019 to 2025). A benign or malignant brain and spinal cord tumor that arises from glial cells (astrocytes, oligodendrocytes, ependymal cells). "Here, we analyzed ITGB4 expression in glioma and its association with glioma prognosis on TCGA and CGGA." (PMID 38172503, 2024). "Bioinformatics analysis suggests that Itgb4 expression is lower in IDH1-mutant gliomas, and lower Itgb4 levels are associated with better prognosis." (PMID 38982076, 2024). "Elevated levels of ITGB4 maintained the stem-like properties of GSCs, promoted glioma cell migration and tumorigenesis, and were associated with glioma grades." (PMID 30658712, 2019). "Finally, by integrating data from the CGGA and TCGA databases, it was validated that ITGB4 expression was lower in IDH1-mutant gliomas, and patients with lower ITGB4 expression were associated with better prognosis." (PMID 38982076, 2024). "Additionally, ITGB4 is closely related to immune cell infiltration in the glioma TME, and specifically interacts with tumor associated fibroblasts." (PMID 38172503, 2024). "Immune cell infiltration and single cell sequencing analyses indicated that ITGB4 may be closely related to the microenvironment of gliomas, especially tumor-associated fibroblasts." (PMID 38172503, 2024). "This suggests that IDH1 mutation and TMZ treatment decrease ITGB4 expression in gliomas." (PMID 38982076, 2024). "For example, GKLF, also known as KLF4, showed a highly significant result and is known to be involved in the self-renewal of glioma stem cells and glioma-genesis through its interaction with ITGB4." (PMID 41007824, 2025). "Collectively, these studies unveil a novel feedback loop linking KLF4 and ITGB4 that contributes to the self-renewal of glioma stem cells and the development of gliomas." (PMID 40034124, 2025). "Univariate and multivariate analysis also showed that ITGB4 was a poor prognostic factor in lower grade glioma." (PMID 38172503, 2024). "Current research has demonstrated that ITGB4 is a critical molecule in maintaining glioma stemness and promoting glioma growth." (PMID 38982076, 2024). "To explore the biological functions of Itgb4 in glioma and treatment, we established cell lines with altered Itgb4 levels and assessed their proliferation capacity and sensitivity to D-2HG." (PMID 38982076, 2024). "In gliomas, ITGB4 demonstrates high expression and serves as a reliable prognostic indicator for low-grade tumors, as confirmed by both bioinformatic analysis and tissue sample comparison." (PMID 39169946, 2024). "Subsequently, we introduced unprecedented evidence demonstrating that D-2HG inhibits glioma cell proliferation and enhances apoptosis by down-regulating the ITGB4/PI3K/AKT pathway." (PMID 38982076, 2024). "To further explore the role of Itgb4 in gliomas, we analyzed the relationship between Itgb4 expression and IDH1 status in both CGGA and TCGA databases." (PMID 38982076, 2024). "Here, we found that ITGB4 is upregulated in glioma and accurately predicts the prognosis of lower grade glioma (LGG)." (PMID 38172503, 2024). "Overexpression of ITGB4 is correlated with poor prognosis in several cancers, including small-cell lung carcinoma, low-grade glioma, and hepatocellular carcinoma." (PMID 39152432, 2024). "The results above showed that ITGB4 is highly expressed in tumors and is an independent prognostic factor in gliomas, especially LGG." (PMID 38172503, 2024). "Some studies have found that ITGB4 expression was increased in glioma stem cells and human glioma tissues." (PMID 38172503, 2024). "First, we divided all glioma patients on TCGA into the high and the low expression groups based on median ITGB4 expression level." (PMID 38172503, 2024). "The transcription factor, KLF4 and ZKSCAN3, facilitate ITGB4 expression respectively in glioma and liver cancer by directly binding to its promotor." (PMID 35305660, 2022).
glioma (continued). "Inhibition of ITGB4 expression in glioma cells reduced the self-renewal abilities of GSCs and suppressed glioma cell migration and proliferation in vitro and in vivo." (PMID 30658712, 2019). "The IHC staining indicated that ITGB4 expression levels were increased in human glioma samples relative to normal brain tissues." (PMID 30658712, 2019). "To further verify this, we examined the mRNA levels of ITGB4 in seven glioma tissues and three normal brain tissues from our own institution." (PMID 30658712, 2019). "Inhibition of ITGB4 in glioma cells would decrease the self-renewal abilities of glioma stem cells and suppress the malignant behaviors of glioma cells in vitro and in vivo." (PMID 31875161, 2019). "Further mechanistic studies revealed that KLF4, an important transcription factor, directly binds to the promoter of ITGB4, facilitating its transcription and contributing to increased ITGB4 expression in glioma." (PMID 30658712, 2019). "Inhibition of ITGB4 in glioma cells decreased the self-renewal abilities of GSCs and suppressed the malignant behaviours of glioma cells in vitro and in vivo." (PMID 30658712, 2019). "Subsequently, we found that ITGB4 knockdown decreased the self-renewal abilities of GSCs and suppressed glioma cell migration and proliferation in vitro and in vivo." (PMID 30658712, 2019). "Increased ITGB4 levels played an oncogenic role in glioma and were correlated with the glioma grades." (PMID 30658712, 2019). "Here, we found that KLF4 directly binds to the promoter of ITGB4, facilitating its transcription and contributed to ITGB4 increase in glioma." (PMID 30658712, 2019). "To assess the contribution of ITGB4 in promoting glioma stem-like properties, we first obtained ITGB4-positive cells from the LN229 and U251 cells by fluorescence-activated cell sorting (FACS)." (PMID 30658712, 2019). "Subsequently, the mRNA levels of ITGB4 were assessed in 81 glioma tissues and 23 normal brain tissues, using gene expression data obtained from the Oncomine database." (PMID 30658712, 2019). "Moreover, our external database validation revealed lower Itgb4 expression in IDH1-mutant gliomas, correlating with a more favorable prognosis." (PMID 38982076, 2024). "And our research also suggests that ITGB4 may serve as a potential therapeutic target for gliomas, and D-2HG may exert anti-glioma effects by inhibiting ITGB4." (PMID 38982076, 2024). "Moreover, our findings suggest ITGB4 as a promising therapeutic target for gliomas and lay the groundwork for the translational development of D-2HG as a potential anti-glioma therapeutic agent." (PMID 38982076, 2024). "Next, stratification analysis was done to evaluate the impact of ITGB4 in glioma prognosis." (PMID 38172503, 2024). "Furthermore, we examined the relationship between Itgb4 expression and the prognosis of glioma patients." (PMID 38982076, 2024). "This research endeavor contributes to a more comprehensive understanding of the role of D-2HG and ITGB4 in glioma and may facilitate the development of more effective therapeutic strategies." (PMID 38982076, 2024). "Cell experiments for the first time reveal that the IDH1 mutation byproduct, D-2HG, effectively inhibits the ITGB4/PI3K/AKT pathway, thus exerting potent anti-glioma effects and offering insights into its mechanism of action, including its synergistic effect with TMZ." (PMID 38982076, 2024). "Finally, the expression of ITGB4 in glioma and its relationship with overall survival (OS) were analyzed using immunohistochemistry." (PMID 38172503, 2024). "Immunohistochemistry was then used to validate the expression and role of ITGB4 in glioma." (PMID 38172503, 2024). "In addition, we further analysed the correlation between KLF4 and ITGB4 in human glioma tissues (n = 112)." (PMID 30658712, 2019). "In this study, our findings showed that ITGB4 expression was increased in GSCs and glioma tissues." (PMID 30658712, 2019).
glioma (continued). "Similarly, we found that the mRNA and protein levels of ITGB4 were increased in human glioma and GSCs." (PMID 30658712, 2019). "Interestingly, increased ITGB4 levels were found in high-grade gliomas and high ITGB4 expression was significantly correlated with increased tumour grade." (PMID 30658712, 2019). "The binding assays suggested that ITGB4 could interact with KLF4 in glioma cells and they were co-localization in the cells." (PMID 30658712, 2019). "Additionally, we also found that knockdown of ITGB4 increased the ubiquitylation of KLF4 in glioma cells, while overexpression of ITGB4 decreased the ubiquitylation of KLF4." (PMID 30658712, 2019). "In this study, we found that ITGB4 expression was increased in GSCs and human glioma tissues." (PMID 30658712, 2019). "Given that ITGB4 suppression diminished GSC properties in vitro, we then examined whether ITGB4 knockdown could affect glioma cell migration and proliferation in vitro and in vivo." (PMID 30658712, 2019). "To better understand the role of ITGB4 in the development of human glioma, we further examined ITGB4 expression in human glioma samples (n = 112; World Health Organization (WHO) grade II–IV) and nonneoplastic brain tissue samples (n = 8) by immunohistochemical (IHC) staining." (PMID 30658712, 2019). "Although ITGB4 has been reported to promote tumourigenesis in many cancers, its role in glioma is still unknown." (PMID 30658712, 2019). "Further mechanistic studies revealed that KLF4, an important transcription factor, could directly bind to the promoter of ITGB4, facilitating its transcription and contributing to increased ITGB4 expression in glioma." (PMID 30658712, 2019). "However, few studies have investigated the role of ITGB4 in gliomas, especially LGGs." (PMID 38172503, 2024). "Thus, inhibiting ITGB4 reduces the self-renewal ability, thereby hindering glioma development." (PMID 38982076, 2024). "Similarly, increased ITGB4 mRNA expression was observed in the glioma tissues." (PMID 30658712, 2019). "In glioma, KLF4 directly binds to the ITGB4 promoter, promoting its transcription and contributing to increased expression of ITGB4 in glioma." (PMID 40034124, 2025). "In a remarkable feedback loop, ITGB4 interacted with KLF4 and reduced its binding to E3 ligase VHL in glioma cells, thereby enhancing KLF4 stability and increasing KLF4 expression." (PMID 40034124, 2025). "Simultaneously, we found that ITGB4 interacted with KLF4 and decreased its binding to the E3 ligase VHL in glioma cells, which subsequently enhanced KLF4 stability and increased KLF4 expression." (PMID 30658712, 2019). "Taken together, our data suggests the existence of a positive feedback loop between KLF4 and ITGB4 that promotes GSC self-renewal and gliomagenesis, and also implicates ITGB4 as a valuable therapeutic target for glioma." (PMID 30658712, 2019). "To examine the involvement of ITGB4 expression in glioma tumorigenesis in vivo, we implanted LN229 cells, stably expressing control shRNA or shRNA targeting ITGB4, into nude mice." (PMID 30658712, 2019). "To further confirm this, we next enriched glioma stem cells from LN229 and U251 cells by ALDH1- positive sorting assay and found that ALDH1+ cells also exhibited much higher ITGB4 mRNA and protein expression levels than ALDH1− cells." (PMID 30658712, 2019). "In our experimental model, D-2HG demonstrated potential anti-glioma effects by inhibiting the expression of Integrin subunit beta 4 (ITGB4), which subsequently downregulated the phosphorylation levels of PI3K and AKT, ultimately suppressing glioma cell proliferation and promoting apoptosis." (PMID 38982076, 2024). "Results showed that IDH1 wild-type gliomas without TMZ had the highest ITGB4 expression, while IDH1-mutant gliomas with TMZ had the lowest." (PMID 38982076, 2024).
glioma (continued). "Furthermore, although not correlating to response to irradiation, recent studies have shown that COL1A1, ITGA7, ITGB3, ITGB4, HMMR and IBSP upregulation confer low survival rate to glioma patients." (PMID 34211843, 2021). "Thus, our study reveals that a novel feedback loop exists between KLF4 and ITGB4, which contributes to GSC self-renewal and glioma tumourigenesis." (PMID 30658712, 2019). "Collectively, our data indicate the existence of a positive feedback loop between KLF4 and ITGB4 that promotes GSC self-renewal and gliomagenesis, suggesting that ITGB4 may be a valuable therapeutic target for glioma." (PMID 30658712, 2019). "Interestingly, when ITGB4 levels were increased, it was able to interact with KLF4 and thus decrease its binding to the E3 ligase VHL, leading to its accumulation in glioma." (PMID 30658712, 2019).
hepatocellular carcinoma (14 papers, 2018 to 2026). A malignant tumor that arises from hepatocytes. "Upregulation of ITGB4 partially reverses the decrease in hepatocellular carcinoma cell invasion and migration caused by SPC25 silencing." (PMID 39169946, 2024). "It was shown that EGFR cooperated with integrin β4 (ITGB4) to promote anchorage-independent growth and metastasis of hepatocellular carcinoma." (PMID 30479571, 2018). "A previous study showed that ITGB4 affected anoikis through interacting with EGFR in hepatocellular carcinoma." (PMID 30479571, 2018). "The influence of ITGB4 extends to hepatocellular carcinoma as well." (PMID 39169946, 2024). "Moreover, ITGB4 promotes metastasis of hepatocellular carcinoma by conferring anchorage independence through EGFR‐dependent FAK‐AKT activation." (PMID 36507553, 2023). "Furthermore, ITGB4 cooperates with EGFR to foster resistance to anoikis in hepatocellular carcinoma." (PMID 36076232, 2022). "ITGB4 functions as an upstream regulator of FAK, exerting a significant impact on AKT phosphorylation in non-small cell lung cancer (NSCLC) and hepatocellular carcinoma." (PMID 39169946, 2024). "Similarly, in hepatocellular carcinoma (HCC), hypoxia-induced integrin β4 (ITGB4) activates the TGF-β/Smad pathway, promoting lactate secretion that transforms hepatic stellate cells (HSCs) into CAFs marked by elevated α-SMA and vimentin expression." (PMID 40565047, 2025). "Moreover, higher ITGB4 expression level was detected in tumor than adjacent non-tumor tissues in patients with hepatocellular carcinoma (HCC)." (PMID 31875161, 2019).